RTL3 (retrotransposon Gag like 3)
Description:
May function as a transcriptional regulator. Plays a role in postnatal myogenesis, may be involved in the regulation of satellite cells self-renewal.
Synonyms: MAR3; MART3; ZCCHC5; FLJ38865; ZHC5; SIRH9
Tractability: Antibody: the Human Protein Atlas places it where antibodies can reach.
Gene: Protein-coding gene on chromosome X (78,656,068 to 78,659,532, reverse strand). Ensembl gene ENSG00000179300.
Subcellular location: Nucleus
Subcellular location (Human Protein Atlas): Nucleoplasm; Golgi apparatus; Plasma membrane
Gene Ontology:
Molecular function: nucleic acid binding; zinc ion binding
Cellular component: nucleus
Homologues: Orthologues: rabbit RTL3 (69% identical), mouse Rtl3 (60% identical), rat Rtl3 (57% identical). Paralogues in human: RTL5 (20% identical), PEG10 (18% identical), RTL1 (15% identical), RTL4 (13% identical), RTL10 (12% identical), LDOC1 (9% identical), RTL6 (8% identical), RTL8A (8% identical), RTL8B (8% identical), RTL8C (7% identical).
Diseases named in the same sentence as RTL3 in open-access papers:
RTL3 is named in the same sentence as 4 diseases in open-access papers, as found by Europe PMC text mining. Sharing a sentence is not in itself a finding about the gene and the disease. The quoted sentences say what the papers report.
infection (1 paper, 2015). The state of being infected such as from the introduction of a foreign agent such as serum, vaccine, antigenic substance or organism. "We indeed observed that RTL1, but not RTL2 or RTL3, is induced in leaves in response to infection by viruses from four different families, consistent with a possible role of RTL1 in plant–virus interactions." (PMID 26696443, 2015).
RTL3 also shares sentences with these, for which no sentence is quoted: cancer (1 paper); tumor (1); virus infection (1).